PTH (parathyroid hormone)
Diseases named in the same sentence as PTH in open-access papers (continued):
Sharing a sentence is not in itself a finding about the gene and the disease.
osteoarthritis (continued). "PTH has been reported to inhibit cartilage degradation, terminal differentiation, and apoptosis of chondrocytes and to promote regeneration of articular cartilage in osteoarthritis." (PMID 33646122, 2021). "PTH prevents cartilage degeneration and/or the deterioration of subchondral bone, induces cartilage regeneration or chondrocytes proliferation in osteoarthritis, and stimulates subchondral bone and articular cartilage repair of focal osteochondral defects." (PMID 33646122, 2021). "The 50% PWT of vehicle mice continued to worsen from week 2 onward, but the 50% PWT of PTH mice stabilized at levels significantly higher than those of vehicle mice, indicating that iPTH initiated early in the development of osteoarthritis reduced secondary hyperalgesia." (PMID 33646122, 2021). "In this study, we investigated whether intermittent parathyroid hormone (iPTH) could attenuate osteoarthritis pain by modifying cartilage degeneration, subchondral bone microarchitecture, and subchondral sensory innervation." (PMID 33646122, 2021). "These compounds can stimulate the formation of parathyroid hormone, receptor-mediated cAMP and may be useful in the treatment of degenerative arthritis, osteoarthritis and rheumatoid arthritis both locally and systemically." (PMID 33906691, 2021). "This drug has already been approved by the US Food and Drug Administration (FDA), and could be used in clinical trials to see if PTH has the same beneficial effects on patients with osteoarthritis." (PMID 33646122, 2021). "However, Tb.Pf of PTH mice was significantly lower than that of vehicle mice, which indicates that early initiation of iPTH slowed the disruption of subchondral trabecular bone connectivity in osteoarthritis." (PMID 33646122, 2021). "PTH has been shown to inhibit the expression of pro-inflammatory modulators, including COX2, in the synovial membrane of the osteoarthritis animal models." (PMID 33646122, 2021). "We found that PTH reduced sensory innervation and the level of PGE2 in subchondral bone through inhibition of aberrant subchondral bone remodeling, which resulted in osteoarthritis pain relief." (PMID 33646122, 2021). "In total, 48 with early osteoarthritis (EOA) and 48 matched controls were selected, and serum 25(OH)D and parathyroid hormone (PTH) levels were analyzed." (PMID 34836290, 2021). "To examine the effect of iPTH on osteoarthritis pain, we generated a DMM model of osteoarthritis in 10 week old mice, administered daily PTH subcutaneously beginning 3 days after surgery, and assessed pain behavior during the following 8 weeks." (PMID 33646122, 2021). "Previous studies have shown that PTHR1 expression is upregulated in cartilages with progressive osteoarthritis, which could benefit us when treating TMJOA with PTH." (PMID 40522441, 2025). "Considering that the articular cartilage has no nerve and blood vessel, PTH-induced decrease of osteoarthritis pain is primarily due to its effect on subchondral bone." (PMID 33646122, 2021). "In the Pth1r−/− mice after DMM surgery, PTH failed to improve osteoarthritis pain and reduce the sensory innervation and the level of PGE2 in the subchondral bone, but PTH worked effectively in Pth1r+/+ mice." (PMID 33646122, 2021). "The result of PTH induction of osteoarthritis was conducted in normal mice rather than osteoarthritis animal models." (PMID 33646122, 2021). "Patients’ pain and functional capacity through outcome measures—knee-injury osteoarthritis outcome scale (KOOS) and Karnofsky performance scale (KPS), biomarkers such as levels of CPR, PTH and 25-hydroxy-vitamin-D were evaluated for the groups with and without supplement using appropriate kits." (PMID 31766751, 2019). "Intermittent PTH attenuated the increases of Nestin+ and Osterix+ cells in subchondral bone marrow of DMM mice, suggesting that early initiation of iPTH attenuates aberrant bone formation in osteoarthritis by modulating the recruitment of osteoprogenitors in subchondral bone." (PMID 33646122, 2021).
Sepsis (20 papers, 2013 to 2025). Sepsis is defined as life-threatening organ dysfunction caused by a dysregulated host response to infection. "Here, we identified Calca, encoding the sepsis biomarker procalcitonin (ProCT), as a novel target gene of PTH in murine osteoblasts that inhibits osteoclast formation." (PMID 35087025, 2022). "In conclusion, low 1,25(OH)2D levels are associated with increased 30-day mortality in sepsis patients, likely due to impaired 25(OH)D hydroxylation and PTH insensitivity." (PMID 23741318, 2013). "It is hypothesized that sepsis causes the impaired secretion of parathyroid hormone, increases the organ resistance to parathyroid hormone or promotes influx from the blood to tissues." (PMID 36424547, 2022). "It is known that inflammatory cytokines induce a lower parathyroid hormone (PTH) secretion as well as a PTH resistance in kidneys and bones during sepsis." (PMID 33315933, 2020). "Recently, using a murine model of sepsis, it was found that the osteoblast number and activity were suppressed during sepsis but the administration of PTH rescued bone development." (PMID 33182721, 2020). "In all neonatal foals, sepsis score was negatively correlated with total calcium (rs = - 0.27; P = 0.005) and positively correlated with phosphorus (rs = 0.25; P = 0.01) and PTH concentrations (rs = 0.40; P = 0.0001)." (PMID 26046642, 2015). "Hence, also similar to human sepsis patients, sepsis mice displayed suppressed blood 1,25(OH)2D levels which cannot be overcome by increased blood PTH levels." (PMID 31791247, 2019). "We note that sepsis shock syndrome represents loss of regulation of inflammatory response to infection and that vitamin D, parathyroid hormone, fibroblast growth factor, and klotho interact with sepsis defense mechanisms in which movement of calcium and phosphorus are part of the process." (PMID 30134544, 2018). "We demonstrated in both human subjects and mice that sepsis-associated 1,25(OH)2D deficiency could not be overcome by increased production of PTH which stimulates 1α-hydroxylase." (PMID 31791247, 2019). "In addition to these changes in vitamin D and PTH we also found that the serum calcium was significantly decreased in the non-survivors compared with the survivors, possibly as a result of the inflammatory response in sepsis." (PMID 23741318, 2013). "The fact that we observed significantly high levels of PTH in our study suggests that degradation of PTH from storage would not invalidate our conclusion that the renal 1α-hydroxylase and 1,25(OH)2D production are insensitive to PTH stimulation in sepsis." (PMID 23741318, 2013).
Anxiety (19 papers, 2016 to 2025). Intense feelings of nervousness, tension, or panic often arise in response to interpersonal stresses. "In conclusion, the study found a strong association between levels of parathyroid hormone and Vit D, sleep quality, and anxiety symptomatology in patients suffering from GAD." (PMID 36901441, 2023). "The risk of anxiety was increased by 0.5% (OR = 1.005, 95% CI: 1.002–1.009) for every unit increase in blood PTH level, but it decreased by 3.9% (OR = 0.961, 95% CI: 0.926–0.998) for each unit increase in Hb in the MHD patients." (PMID 37046867, 2023). "In addition, another study concluded that anxiety was negatively associated with intact PTH (iPTH) levels." (PMID 38681457, 2024). "In our sample, the regression analysis confirmed the significant association between higher PTH and lower Vit D levels, poor quality of sleep, and anxiety symptomatology emphasizing the close relationship between calcium imbalance and psychopathology in patients with GAD." (PMID 36901441, 2023). "Patients in the study group were 2.934 times more subjected to the incidence of anxiety than the control group (OR: 2.934, 95%CI 1.394-6.175, p = 0.05) due to varying levels of serum PTH levels." (PMID 38681457, 2024). "The study results suggest that patients with GAD and low levels of Vit D and higher levels of PTH exhibit poor quality of sleep and higher levels of anxiety highlighting its impact on the psychopathological burden." (PMID 36901441, 2023). "We also found that high endogenous creatinine, PTH, and hemoglobin levels and decreased creatinine clearance were positively correlated with anxiety symptoms, which was consistent with previous studies." (PMID 37176560, 2023). "Patients with anxiety symptoms had higher levels of endogenous creatinine, parathyroid hormone, and hemoglobin, as well as decreased creatinine clearance, being younger and less educated." (PMID 37176560, 2023). "Patients with anxiety symptoms had higher levels of endogenous creatinine, PTH, and hemoglobin, as well as decreased creatinine clearance." (PMID 37176560, 2023). "In conclusion, there appears to be good evidence that a locally derived plasma PTH RI is required for an adult UK population to prevent inappropriate patient anxiety and follow up." (PMID 37139470, 2023). "The study findings suggest that patients with GAD and low levels of Vit D and higher levels of PTH exhibit insomnia, poor quality of sleep, and higher levels of anxiety, highlighting its impact on the psychopathological burden." (PMID 36901441, 2023). "In the present study, age, CRP, Alb, Ca2+, PTH and anxiety were used as predictors to develop a prediction model for sleep disturbance in MHD patients." (PMID 35959399, 2022). "Similarly, in the case of anxiety, for individuals with PTH levels >400 pg/ml, 17, 9, and 36 cases were classified as abnormal, borderline, and normal, respectively." (PMID 38681457, 2024). "Thus, an imbalance of PTH and Vit D levels predicted insomnia, higher levels of anxiety, and poor quality of sleep." (PMID 36901441, 2023). "Furthermore, creatinine, parathyroid hormone, hemoglobin levels, creatinine clearance, and education affected the anxiety scale score." (PMID 37176560, 2023). "Although further studies on the brains of animal models of PS-HypoPT are much needed, we can hypothesize that memory impairment and anxiety behavior in PS-HypoPT could be related to PTH deprivation effects on the hippocampus and amygdala, even if mechanisms are yet to be elucidated." (PMID 38392648, 2024). "Furthermore, age, CRP, Alb, Ca2+, PTH and anxiety were screened by two-way stepwise regression." (PMID 35959399, 2022). "While one study reported a small positive correlation between anxiety and serum PTH levels (r = 0.1797, p < 0.05), others did not, nor to a potential correlation with serum cortisol." (PMID 39997061, 2025).
iron deficiency (19 papers, 2017 to 2025). "Parathyroid hormone and thyrotropin remained within the bounds of what is considered an accepted range in HD patients (×2–9 normal PTH levels), whereas sideropenia, or low iron levels, confirmed the presence of iron-deficiency anaemia." (PMID 41153672, 2025).
rheumatoid arthritis (19 papers, 2009 to 2025). A chronic, systemic autoimmune disorder characterized by inflammation in the synovial membranes and articular surfaces. "GSEA analysis indicated that OSA is predominantly associated with an IL-17 signaling pathway, pertussis, rheumatoid arthritis, parathyroid hormone synthesis, secretion, and action, TNF signaling pathway, amyotrophic lateral sclerosis, and non-alcoholic fatty liver disease." (PMID 34880901, 2021). "This study demonstrated that there is an increase in serum intact PTH level in 8% of rheumatoid arthritis patients, which indicates an imbalance in the level of the hormone as a result or cause of RA." (PMID 37858254, 2023). "Downregulated genes are enriched in parathyroid hormone synthesis, secretion and action, rheumatoid arthritis, and endocrine and other factor-regulated calcium reabsorption." (PMID 38137348, 2023). "The relationship between rheumatoid arthritis and parathyroid hormone is not yet fully understood due to the many factors that influence parathyroid hormone levels in the blood." (PMID 37849009, 2023). "The parathyroid hormone (PTH) is the marker for thyroid function, and the receptor activator nuclear factor-B biomarker is the marker for rheumatoid arthritis." (PMID 37110837, 2023). "A growing body of evidences support an essential role of Th17 cells in gut-bone axis, especially in bone loss associated with menopause, periodontal disease, parathyroid hormone (PTH) and rheumatoid arthritis." (PMID 36726994, 2022). "It has been shown that TNF inhibition increases serum PTH levels in patients with rheumatoid arthritis." (PMID 33861790, 2021). "TNF inhibitor increased serum PTH level in patients with rheumatoid arthritis." (PMID 33861790, 2021). "This study aimed to compare vitamin D receptor (VDR) FokI and TaqI genotypes in terms of parathyroid hormone (PTH) and some biomarkers of inflammation and susceptibility to rheumatoid arthritis (RA) disease." (PMID 37858254, 2023). "The relationship between rheumatoid arthritis (RA) and parathyroid hormone (PTH) levels is ambiguous and unclear." (PMID 37849009, 2023). "MCP-1 expression has already been detected at sites of tooth eruption, bone metastasis and Rheumatoid Arthritis, being regulated by inflammatory cytokines such as TNF-α and Interleukin (IL)-1b and hormones, such as PTH." (PMID 25229495, 2014). "Third, there were residual confounders that were not included in the model for adjustment, such as parathyroid hormone, rheumatoid arthritis, and hip osteoarthritis." (PMID 38982346, 2024). "FokI but not TaqI genotypes had an effect on serum intact PTH level in rheumatoid arthritis patients." (PMID 37858254, 2023). "Serum intact PTH level in rheumatoid arthritis patients did not correlate to ESR, CRP, RF, or ACCPs in rheumatoid arthritis patients, so serum intact PTH level did not predict susceptibility to RA or disease severity according to the previous biomarkers." (PMID 37858254, 2023).
diabetic nephropathy (18 papers, 2016 to 2026). "Studies confirmed disturbances in serum calcium, phosphate and vitamin D levels, parathyroid hormone (PTH) metabolism, and dysregulation of bone turnover, primarily attributed to progressive eGFR decline associated with diabetic nephropathy." (PMID 39735781, 2024). "Disrupted serum calcium and urine albumin excretion are considered as modifiable risk factors for CKD progression that may help in early preventive measures serum calcium is tightly linked to altered vitamin D3 and intact PTH levels in patients with DM and diabetic nephropathy." (PMID 37312131, 2023). "There were significant differences in sex, presence of diabetic nephropathy, HD vintage, serum albumin, serum phosphate, C-reactive protein, intact parathyroid hormone, Kt/V, and GNRI." (PMID 29558928, 2018). "Lower levels of PTH in diabetic nephropathy patients may generate a low turnover state, and this poor bone turnover condition may lead to a higher risk of fracture by causing microdamage buildup and increased fragility." (PMID 39791168, 2025). "In this study, 25-hydroxyvitamin D, BGP, β-CTX, PTH, T-PINP, and ultrasound BMD are combined to diagnose early diabetic nephropathy, which is of great clinical value." (PMID 37250586, 2023). "The area under the curve (AUC) of 25-hydroxy-vitamin D, PTH, BGP, β-CTX, T-PINP and ultrasound BMD were 0.910, 0.826, 0.841, 0.822, 0.821, 0.811 respectively in the diagnosis of early diabetic nephropathy, and the AUC of combined diagnosis was 0.995." (PMID 37250586, 2023). "Already in the 1980s, it was shown that patients with diabetic nephropathy have a lower bone mass than non-diabetic CKD patients and that circulating parathyroid hormone (PTH) levels are relatively low." (PMID 32857288, 2020).
myocardial infarction (18 papers, 2008 to 2025). Gross necrosis of the myocardium, as a result of interruption of the blood supply to the area, as in coronary thrombosis. "In rats with induced myocardial infarction PTH application led to mobilization of angiogenic progenitor cells from bone marrow and improved survival and reduced infarct size compared to sham treatment, probably via promoting VEGF-mediated cardiac neovascularization." (PMID 28406904, 2017). "However, even without associated disturbances in serum PTH, serum calcium per se in the reference range is positively associated with cardiovascular endpoints such as myocardial infarction." (PMID 25924883, 2015). "However, there has been a lack of data on the associations between P, Ca, and intact PTH levels and individual cardiovascular end points such as myocardial infarction (MI), hemorrhagic stroke, or ischemic stroke." (PMID 25494334, 2014).